INS (insulin)
Diseases named in the same sentence as INS in open-access papers (continued):
Sharing a sentence is not in itself a finding about the gene and the disease.
Hyperinsulinemia (continued). "Uremic patients have abnormal glucose and insulin metabolism and this glucose load could contribute to some metabolic abnormalities such as hyperinsulinemia or reduced peripheral sensitivity to insulin." (PMID 26986485, 2016). "Postprandial hyperinsulinemia is a risk factor for development of laminitis, and since EMS is a rising concern in the equine population worldwide, it is important to create appropriate diagnostic tests for abnormalities in insulin regulation." (PMID 27766982, 2016). "Hyperinsulinemia reduces insulin-mediated glucose uptake and also enhances steroidogenesis." (PMID 26770659, 2016). "Evidence from in vitro and in vivo experimental studies has shown that insulin, it’s analogs and oral insulin secretagogues (such as sulfonylureas), which may contribute to hyperinsulinemia, are suggested to increase the incidence and progression of cancer." (PMID 27642100, 2016). "This binding occurs when insulin reaches high concentrations, as compensatory hyperinsulinemia." (PMID 27423183, 2016). "Hyperinsulinemia may be endogenous because of insulin resistance, or exogenous due to the administered insulin or insulin secretagogues." (PMID 26983499, 2016). "Hyperinsulinemia may play a crucial role as an important factor in the onset or progression of HCC through up-regulation of insulin signal cascades." (PMID 26913058, 2016). "An interesting aspect that deserves attention concerns the effects of compensatory hyperinsulinemia: although it is usually considered a by-product of the insulin resistance, hyperinsulinemia exerts its effects, overstimulating certain pathways of insulin action in various cells." (PMID 27437032, 2016). "Insulin-sensitizers improve the metabolic and hormonal profile in PCOS patients and may also act as anticancer agents, especially in cancers associated with hyperinsulinemia and oestrogen dependent cancers." (PMID 27725832, 2016). "While PCOS is robustly associated with impaired insulin sensitivity and hyperinsulinemia, this is independent of body weight, and a significant proportion of insulin-resistant women with PCOS are lean." (PMID 27375552, 2016). "Recent evidence supports the hypothesis that reduced insulin sensitivity and hyperinsulinemia are among the most important factors leading to renal injury." (PMID 27087488, 2016). "It is possible that severe hyperinsulinism in children with CHI may play a causal role in the pathogenesis of persistent FPs, consistent with observations that insulin signaling in the brain may regulate feeding behavior in animals." (PMID 26903946, 2016). "Further studies are required to evaluate the longer term natural history of FPs and to investigate how insulin alters feeding behavior and whether prompt treatment of hyperinsulinism may prevent FPs in children with CHI." (PMID 26903946, 2016). "Overall, findings demonstrate reduced baseline hepatic glucose production, impaired insulin sensitivity with lower rate of glucose infusion to achieve euglycemia, and suppression of endogenous hepatic glucose production in response to hyperinsulinemia in the steady-state." (PMID 25883986, 2015). "The high leptin in hyperinsulinemia of PCOS women may be a secondary consequence of insulin-stimulated leptin synthesis." (PMID 26180527, 2015). "IR-A overexpression in cancer has helped us in explaining recent findings indicating that high levels of circulating insulin (hyperinsulinemia) may be related to cancer." (PMID 25798130, 2015). "Furthermore, there was a trend for insulin levels to be greater in obese animals (p = 0.06), indicating the hyperinsulinemia." (PMID 26390297, 2015). "In addition, reducing insulin sensitivity of skeletal muscle, FFA inhibit glucose uptake and consequently raise circulating glucose levels which increase the pancreatic insulin secretion and lead to hyperinsulinemia." (PMID 26198245, 2015).
Hyperinsulinemia (continued). "Furthermore, hyperinsulinemia reduces urinary uric acid excretion by the effect of insulin on urinary tubules leading to hyperuricemia." (PMID 26380228, 2015). "It is possible that hyperinsulinemia induces GnRH secretion via activation of the IGF-1 receptor which can bind insulin at high doses, but the reduction in GnRH secretion we observed upon deletion of the IR in the neuron suggests that activation is occurring via insulin receptor signaling." (PMID 25780937, 2015). "Because hyperinsulinemia and IR are the crucial pathogenic signals for the development of NASH, in this study, we also found that insulin stimulation in vitro could lead to AKT, p-MDM2, MDM4 activation and impaired autophagy." (PMID 25826083, 2015). "Fasting insulin concentration ranged from 5.2 to 59.9 μU/mL, but ~50% present hyperinsulinemia." (PMID 26089900, 2015). "However, it has also been suggested that adiponectin concentrations are themselves regulated by insulin and that low adiponectin observed in settings of low insulin sensitivity are due to compensatory hyperinsulinemia." (PMID 26703682, 2015). "Acute hyperinsulinemia (induced by intravenous (IV) insulin infusion) increases Aβ1-42 peptide levels in human cerebrospinal fluid (CSF) in an age-dependent fashion in normal, older adults, and has pro-inflammatory effects in the CNS (most notably in the hippocampus and hypothalamus)." (PMID 26340637, 2015). "Data also show that changes in insulin levels, specifically hyperinsulinemia, during pregnancy could induce alterations in hypothalamic organization that may affect metabolism of the offspring later in life." (PMID 25874125, 2015). "In T2D rats, insulin secretion may lose part of this negative regulatory mechanism resulting in hyperinsulinemia, especially in pinealectomized ZDF rats in this study." (PMID 25880500, 2015). "The male MKR mice exhibit hyperinsulinemia by 2–3 weeks of age, and hyperglycemia by 5–6 weeks of age with decreased whole body glucose uptake, failure to suppress hepatic gluconeogenesis in response to insulin and pancreatic beta cell dysfunction." (PMID 25784953, 2015). "A decreased hepatic clearance of insulin may be contributing to the hyperinsulinemia following an oral glucose load." (PMID 26196519, 2015). "Moderate hyperinsulinemia (with euglycemia) induced by IV insulin infusion in healthy, older adults increased Aβ1-42 levels in blood plasma and CSF, as well as increasing CSF levels of certain pro-inflammatory cytokines: interleukins 1a, 1b, and 6 (IL-1a, IL-1b, IL-6,) and TNF-α." (PMID 26340637, 2015). "Likewise, the relationship between hyperinsulinemia and breast cancer was demonstrated using an insulin-resistant and hyperinsulinemic transgenic mouse model." (PMID 25798130, 2015). "Exposure to continuous surges of hyperinsulinemia may overstimulate other tissues that have remained normally responsive to insulin, such as the liver, resulting in a pro-atherogenic lipid profile." (PMID 25705204, 2015). "Using multiple models of mammary carcinoma, these investigators demonstrated that hyperinsulinemia promotes mammary tumor growth and pulmonary metastasis and that treatment with an insulin sensitizer or a small-molecule IR/IGF-IR inhibitor can attenuate these effects." (PMID 26029167, 2015). "This activity suggests that pioglitazone may reduce hyperinsulinemia through accelerating clearance of insulin." (PMID 24740421, 2014). "Such agents could improve glycemic control, prevent compensatory hyperinsulinemia, and possibly delay or obviate the need for exogenous insulin therapy by preserving beta cell function." (PMID 24533136, 2014). "Moreover, we show that hyperinsulinemia is a reflection of high amounts of insulin bound to proteins at a higher proportion than free insulin." (PMID 24995000, 2014).
Hyperinsulinemia (continued). "Insulin-resistant patients with liver steatosis, compared with insulin-sensitive individuals, have greater insulin responses and lower hepatic insulin clearance, leading to hyperinsulinemia." (PMID 24397589, 2014). "In the multiple-step process of insulin clearance, IDE defect may impair insulin clearance and increase the risk for hyperinsulinemia." (PMID 24740421, 2014). "Our results indicate that an excessive extracellular Zn2+ load, resulting from insulin release, may promote β-cell death, which might be particularly important in the context of hyperinsulinemia." (PMID 24502363, 2014). "Increased levels of MIF can enhance insulin secretion in a glucose dependent manner and this may in turn explain the reduced hyperinsulinemia observed in obese MIF−/− mice." (PMID 25412423, 2014). "Interestingly, insulin elevates chemerin in human adipose tissue explants in vitro, and systemic chemerin increases after prolonged hyperinsulinemia in healthy individuals." (PMID 24762064, 2014). "However, hyperinsulinemia is actually augmented during this phase by exogenous insulin because of the inefficiency of exogenous insulin." (PMID 24885616, 2014). "The failure of hepatocytes to respond to insulin contributes to the development of glucose intolerance, whereas lipogenesis, which is positively regulated by insulin, remains sensitive to insulin and is driven excessively by the compensatory hyperinsulinemia." (PMID 25160038, 2014). "Increasing exogenously administered insulin doses results in further peripheral hyperinsulinemia, which may worsen NAFLD." (PMID 24397589, 2014). "As a consequence, these cells produce more insulin that may result in hyperinsulinemia in the fetus." (PMID 25050345, 2014). "Both partial and total deletion of the eNOS gene were able to affect insulin/glucose homeostasis causing hyperinsulinemia but not the overt insulin resistant state induced by HFD." (PMID 25093405, 2014). "Compensatory hyperinsulinemia in response to GC-induced reduction of insulin sensitivity may be attributable to increased beta-cell responsiveness to glucose and/or increased beta-cell mass." (PMID 24423471, 2014). "Since the phosphorylation of IRS1 at Ser302 is substantially induced by hyperinsulinemia, the lower insulin level may also contribute to the less phosphorylation of IRS1 at Ser302 in Cpt1b+/− mouse muscle." (PMID 25309812, 2014). "Because fat accumulation in the liver may affect insulin clearance, it has long been debated whether impaired insulin clearance in patients with NAFLD is one of the causes of hyperinsulinemia." (PMID 24397589, 2014). "Alterations in insulin stimulated trafficking of glucose transporter 4 are an early sign of metabolic dysfunction in Alström mutant mice, providing a possible explanation for the reduced glucose uptake and the compensatory hyperinsulinemia." (PMID 25299671, 2014). "A reduction in insulin clearance is a mechanism of hyperinsulinemia." (PMID 24740421, 2014). "At low doses, hyperinsulinemia occurs prior to glucose elevation suggesting changes in insulin level could be used clinically to predict the approach to a clinically relevant dose (data not shown)." (PMID 24978597, 2014). "Therefore, despite lower fetal oxygen and BCAAs, hyperinsulinemia in the HG + INS fetuses reduces and normalizes skeletal muscle ubiquitin ligase expression." (PMID 24944291, 2014). "All these defects emerge before the development of overt metabolic disease and may provide a possible explanation for the impaired insulin-stimulated glucose uptake and the compensatory hyperinsulinemia." (PMID 25299671, 2014). "We investigated whether the hyperinsulinemia may be related to disrupted liver insulin signaling protein expression." (PMID 24789994, 2014). "Thus, in a positive feedback loop, pancreas overproduces insulin to overcome the resistance, leading to a hyperinsulinemia in early phases of T2DM." (PMID 24574966, 2014).
Hyperinsulinemia (continued). "The marked elevation of insulin levels during the hyperinsulinemic clamp in isoflurane treated ferrets suggests that the observed insulin resistance involves the liver, given that hepatic insulin resistance typically results in impaired hepatic insulin clearance and ensuant hyperinsulinemia." (PMID 24594704, 2014). "Thus, in transgenic mice over-expressing insulin or in patients with insulinomas, the resulting hyperinsulinemia is counteracted by a diminished insulin response." (PMID 25259572, 2014). "Basal hyperinsulinemia may be explained by several factors, including the reduction of hepatic insulin clearance and/or an increase of basal insulin secretion." (PMID 25313308, 2014). "Indeed, in rat pancreatic islets experiments, resveratrol was shown to reduce insulin secretion and this event was confirmed in rats with hyperinsulinemia, in which resveratrol decreased blood insulin levels." (PMID 24734227, 2014). "This adaptive islet compensation leads to a state of hyperinsulinemia together with normoglycemia or a modest increase in glycemic values (prediabetic state) that persist until the β-cells can handle the required demand for insulin." (PMID 25313308, 2014). "Because hyperinsulinemia increases the cleavage of IRs in hepatocytes, we measured the amount of alpha-IR in the conditioned media of primary cultures of rat hepatocytes incubated with different insulin concentrations." (PMID 24995000, 2014). "We and others have previously shown that deletion of GH signaling in liver creates an insulin resistant state with compensatory hyperinsulinemia, disturbed glucose tolerance, and clinical hepatic steatosis from increased TG synthesis and decreased hepatic TG export." (PMID 25566190, 2014). "On the other hand, under an excessive amount of insulin (as in hyperinsulinemia), the hormone competes with Aβ for insulin-degrading enzyme (IDE, a metalloprotease that degrades both insulin and Aβ), allowing for the peptide accumulation and formation of senile plaques." (PMID 25071725, 2014). "This phenomenon may indicate a degree of insulin self-regulation, wherein insulin downregulates its signaling when in excess, such as with the hyperinsulinemia accompanying insulin-resistant states." (PMID 24949486, 2014). "For younger PCOS women, the insulin sensitivity/resistance may be normal or only mild hyperinsulinemia." (PMID 25310961, 2014). "Among these factors, hyperinsulinemia-induced hypertension seems to be an attractive hypothesis in view of the antinatriuretic action of insulin." (PMID 24982885, 2014). "Improved first-phase insulin secretion and subsequent reduced hyperinsulinemia in later postprandial phase may prevent disturbances in glucose metabolism." (PMID 25370913, 2014). "Also, since hyperinsulinemia has been shown to be associated with impaired renal UA clearance the suppressed HYP insulin levels is consistent with the HYP hypouricemia we observed." (PMID 24839967, 2014). "NAFLD may even cause pancreatic β-cells to attempt compensation by increasing insulin production, leading to hyperinsulinemia and in turn, further stimulating hepatic de novo lipogenesis." (PMID 25859286, 2014). "A reduction in the insulin clearance function contributes to hyperinsulinemia." (PMID 24740421, 2014). "Interestingly, we also observed an upregulation of Neurod1 and NKx6.1, which are known to increase transcription of the insulin gene and a reduction in HNF4α transcription, known to occur during hyperinsulinemia (excess levels of insulin in the blood)." (PMID 24806840, 2014). "Moreover, forced overexpression of Slc16a1 in β cells leads to insulin secretion in response to muscle-derived pyruvate and is thought to be responsible for exercise-induced hyperinsulinism in humans." (PMID 25497096, 2014). "Metformin also improves insulin sensitivity in peripheral tissue reducing hyperinsulinemia." (PMID 23936520, 2013).
Hyperinsulinemia (continued). "Moreover, disruption of leptin receptors in β-cells results in increased body weight and adiposity, hyperinsulinemia, impaired glucose-stimulated insulin secretion and insulin resistance." (PMID 23936486, 2013). "This tendency towards altered metabolism became further accentuated in older animals, when neonatally overfed SGA-in-SL rats developed hyperinsulinemia and an increased insulin/glucose ratio under basal conditions (days 360 and 560 of life), indicating insulin resistance." (PMID 24265718, 2013). "The pathological explanation for this connection has led to a so-called hyperinsulinemia hypothesis; increased insulin level could promote colorectal tumor growth and act as a cell mitogen." (PMID 23405123, 2013). "Dependence of Rg′ on plasma insulin level was determined by performing studies in the basal fasting state and during glucose clamps performed at physiologic and superphysiological levels of hyperinsulinemia in Lean, Obese, and Tesaglitazar groups." (PMID 24285952, 2013). "The results showed that the insulin level was increased significantly in the HF-fed mice, while ER treatment markedly suppressed insulin level, indicating the ER could improve hyperinsulinemia in the mice (P<0.05)." (PMID 24312343, 2013). "On the other hand, sustained hyperinsulinemia after a meal due to decreased insulin clearance may have other metabolic effects." (PMID 24194886, 2013). "Although fructose does not appear to increase insulin level acutely, chronic exposure seems to cause hyperinsulinemia indirectly." (PMID 23527159, 2013). "During hyperinsulinemia, plasma insulin levels were comparable between WT and Cox6a2−/− mice." (PMID 23460811, 2013). "In hyperinsulinemia, high concentrations of estradiol can inhibit the excessive insulin signaling in adipocytes, which may be a safety impact both against pathological glucose uptake and dangerous mitogenic activity." (PMID 23061769, 2013). "For instance, excess insulin prenatally, due to hyperinsulinemia in the mother, or postnatally due to overfeeding, can lead to higher insulin concentrations at the level of the hypothalamus, and this may result in changes in brain cell morphology." (PMID 23785312, 2013). "As a consequence, IRS-1 phosphorylation is inhibited leading to lower binding of phosphatidylinositol 3-kinase to IRS-1 and lower translocation of glucose transporter (GLUT-4) to the membrane, stimulated by insulin, with subsequent worsening of hyperglycemia and hyperinsulinemia." (PMID 24084729, 2013). "Considering the fact that altered glucose metabolism occurs in both cases, and hyperinsulinemia with reduced insulin sensitivity is involved, an obvious potential factor affecting the lung is insulin itself, particularly a direct effect on structural cells as well as immune cells in the airway." (PMID 24204385, 2013). "Milk protein consumption results in postprandial hyperinsulinemia in obese subjects, increases body weight of overweight adolescents and may thus deteriorate pre-existing metabolic disturbances of obese, insulin resistant individuals." (PMID 24225036, 2013). "In addition, these animals exhibited reduced glucose/insulin index (−62.5%), and increased insulin secretion during glucose overload (39.3%), and hyperinsulinemia." (PMID 23691518, 2013). "As previously discussed, hyperinsulinemia from increased insulin secretion and decreased insulin clearance correlates with the severity of hepatic steatosis, and chronically elevated plasma insulin levels may promote atherogenesis." (PMID 23509418, 2013). "In conclusion, our data show that NGT 1 h-high have a reduction in insulin clearance as compared with NGT 1 h-low individuals; this suggests that impaired insulin clearance may contribute to sustained fasting and post-meal hyperinsulinemia." (PMID 24194886, 2013). "Therefore, reduction of hyperinsulinemia by P1736 is an indirect evidence of improvement in peripheral insulin sensitivity in ob/ob mice." (PMID 24194903, 2013).